NQO2 (N-ribosyldihydronicotinamide:quinone dehydrogenase 2)
Description:
The enzyme apparently serves as a quinone reductase in connection with conjugation reactions of hydroquinones involved in detoxification pathways as well as in biosynthetic processes such as the vitamin K-dependent gamma-carboxylation of glutamate residues in prothrombin synthesis.
Synonyms: QR2; NMOR2; DHQV; DIA6
Tractability: Small molecule: a structure with a bound ligand is known; a high-quality ligand is known; it has a high-quality binding pocket; it belongs to a druggable protein family. PROTAC: ubiquitination databases record sites on it; its protein half-life has been measured; a small molecule that binds it is known.
Target class: Enzyme; Oxidoreductase
Chemical probes: CHEMBL457992, FURAMIDINE
Gene: Protein-coding gene on chromosome 6 (2,987,987 to 3,022,109, forward strand). Ensembl gene ENSG00000124588.
Subcellular location: Cytoplasm
Subcellular location (Human Protein Atlas): Cytosol; Nucleoplasm
Pathways (Reactome):
Metabolism: Phase I - Functionalization of compounds
Gene Ontology:
Molecular function: chloride ion binding; dihydronicotinamide riboside quinone reductase activity; electron transfer activity; FAD binding; melatonin binding; oxidoreductase activity; oxidoreductase activity, acting on other nitrogenous compounds as donors; protein binding; protein homodimerization activity; resveratrol binding; zinc ion binding; NAD(P)H dehydrogenase (quinone) activity
Biological process: quinone catabolic process
Cellular component: cytosol; extracellular exosome; cytoplasm
Genetic constraint (gnomAD): Loss-of-function variants: 20 observed, 27.16 expected, observed/expected ratio (o/e) 0.74, 90% interval 0.52 to 1.07. The upper end of that interval is the gene's LOEUF score, 1.07, which puts it in group 4 of 6, group 1 being the genes least tolerant of losing a copy. Missense variants: 267 observed, 301.18 expected, observed/expected ratio (o/e) 0.89, 90% interval 0.8 to 0.98. Synonymous variants: 106 observed, 116 expected, observed/expected ratio (o/e) 0.91, 90% interval 0.78 to 1.07.
Homologues: Orthologues: chimpanzee NQO2 (99% identical), macaque NQO2 (92% identical), dog NQO2 (83% identical), mouse Nqo2 (81% identical), rabbit NQO2 (81% identical), guinea pig NQO2 (80% identical), rat Nqo2 (74% identical), pig NQO2 (58% identical), rat AABR07044714.1 (57% identical). Paralogues in human: NQO1 (47% identical).
Diseases named in the same sentence as NQO2 in open-access papers:
NQO2 is named in the same sentence as 45 diseases in open-access papers, as found by Europe PMC text mining. Sharing a sentence is not in itself a finding about the gene and the disease. The quoted sentences say what the papers report.
breast carcinoma (5 papers, 2018 to 2025). "It focuses on the I-29/I-16/D variation and the results link the NQO2 gene to the susceptibility of luminal-like breast cancer." (PMID 33777113, 2021). "In the era of breast cancer subtypes, we would like to study further the relationship between this tri-allelic genetic polymorphism in the NQO2 gene and the risk of breast cancer by molecular subtypes." (PMID 33777113, 2021). "In the present case-control study, we observed a significant association between breast cancer risk and a tri-allelic polymorphism in the NQO2 gene." (PMID 33777113, 2021). "We hypothesized that NQO2 is a candidate susceptibility gene for luminal-like breast cancer because it has a known activity on quinone metabolites derived from estrogen." (PMID 33777113, 2021). "A tri-allelic polymorphism in the NQO2 gene might be associated with the risk of luminal-like breast cancer." (PMID 33777113, 2021). "NQO2, acting as a detoxification enzyme, catalyzes the reduction in electrophilic estrogen quinones (estradiol), revealing a relationship between breast cancer." (PMID 41465541, 2025). "Association between NRH:quinone oxidoreductase 2 (NQO2) tri-allelic polymorphism and breast cancer risk in the whole study population." (PMID 33777113, 2021). "The enrichment for breast cancer in non-Roma is due to variants with increased allele frequencies in ATM, BRCA2, and NQO2 genes." (PMID 34220960, 2021). "In conclusion, several genetic studies suggest rather an important role of NQO2 in breast carcinogenesis, where it seems to be a tumor suppressor at early phases and tumor promoter at later stages of breast cancer development, but there are no functional studies in support of this hypothesis." (PMID 38254976, 2024).
prostate carcinoma (5 papers, 2016 to 2023). A carcinoma that arises from epithelial cells of the prostate gland. "Furthermore, NQO2 was reported to regulate the stability of cyclin D1 in CWR22Rv1 prostate cancer cells by AKT/GSK‐3β signal pathway." (PMID 27165481, 2016). "In addition, NQO2 knockout mouse significantly inhibits prostate cancer cell growth." (PMID 37891619, 2023). "Another aspect of FAN analysis relevant to its utility and implications for the role resveratrol plays in prostate cancer relates to the three primary targets of resveratrol: CSNK2A1, NQO2 and PTGS2." (PMID 27232943, 2016).
Parkinson’s (4 papers, 2013 to 2024). "Recent genetic studies have revealed that many functionally defined and some undefined NQO2 polymorphisms can alter cancer susceptibility and progression, modify the response to chemotherapy, but also may predispose to Parkinson’s disease and certain neurological dysfunctions." (PMID 38254976, 2024). "Clinical studies have shown increased expression of the NQO2 gene in patients with Alzheimer’s and Parkinson’s diseases." (PMID 34884863, 2021).
lung cancer (3 papers, 2020 to 2025). A malignant neoplasm involving the lung. "By targeting NQO2, Afzelin promotes ER stress activation, induces ICD, and inhibits lung cancer proliferation." (PMID 37891619, 2023).
lymph node metastasis (3 papers, 2016 to 2022). "The association between NQO2 I29 homozygosity and lymph node metastasis in PTMC was confirmed in multivariate analysis." (PMID 31428048, 2019). "Patients with PTMC who were homozygous for the NQO2 I29 allele were more likely to have lymph node metastasis at diagnosis compared with PTMC patients bearing the D allele." (PMID 31428048, 2019). "Comparing the expression of NQO1, NQO2, and HOXA11-AS in lymph node metastasis negative cases (pN0) and positive cases (pN1-3), all showed significant differences." (PMID 36142607, 2022).
alcoholism (2 papers, 2008 to 2024). "The 29 bp insertion/deletion (I/D) polymorphism in the promoter region of NQO2 was found to be involved in the pathogenesis of alcoholism and alcohol withdrawal syndrome." (PMID 38254976, 2024). "The I and D promoter variants and other NQO2 polymorphisms may impact cognitive decline, alcoholism and toxicity of several nervous system drugs." (PMID 38254976, 2024).
cognitive decline (2 papers, 2023 to 2024). "So far the genetic studies have not identified NQO2 gene variants predominantly expressed in AD patients or related to the pharmacogenomics of AD therapy, although one study reported the involvement of an exon 3 missense variant of NQO2 in cognitive decline." (PMID 38254976, 2024).
COVID-19 (2 papers, 2022 to 2023). A disease caused by infection with severe acute respiratory syndrome coronavirus 2. "The enzyme NRH:quinone oxidoreductase 2 (NQO2) plays an important role in the pathogenesis of various diseases such as neurodegenerative disorders, malaria, glaucoma, COVID-19 and cancer." (PMID 36770840, 2023).
diabetes (2 papers, 2024 to 2025). "Nqo2 is an antioxidant that may protect against diabetes-induced endothelial dysfunction, whereas Tuba1a is the gene responsible for producing cytoskeleton protein tubulin, a known target for glyoxalase system defect." (PMID 39896461, 2025). "Inhibitors of NQO2 (NRH: quinone oxidoreductase) have potential application in several areas of medicine and pharmacology, including cancer, neurodegeneration (PD and AD), stroke, and diabetes." (PMID 39596096, 2024).
mental disorder (2 papers, 2020). A disease that has its basis in the disruption of mental process. "In addition, Ephx1 and several other genes (Pla2r1, Zmym6, Trappc9, and Nqo2) are annotated in the RGD as genes associated with neurodegenerative diseases and/or mental disorders." (PMID 32429546, 2020). "Although the enrichment does not reach significance following multiple hypothesis testing comparison, it is worth noting that additional genes are implicated in psychiatric disorders (GABRE, GNRH1, FMO1, FLG, SELE, NQO2)." (PMID 33169669, 2020).
ovarian carcinoma (2 papers, 2021 to 2024). A malignant neoplasm originating from the surface ovarian epithelium. "NQO2-3423 G>A (rs2070999) causing higher NQO2 activity in the ovarian tumors was implicated in predisposition to bladder and ovarian cancers, suggesting that NQO2 might be a therapeutic target in these types of cancer." (PMID 38254976, 2024).
psychosis (2 papers, 2011 to 2024). "Another gene which was inhibited was Nqo2 which is involved in oxidation-reduction reactions and has been associated with increased risk of methamphetamine-induced psychosis." (PMID 21886580, 2011).
chronic myelogenous leukemia (1 paper, 2009). "Recent screens carried out to find off-target proteins that bind to imatinib identified the oxidoreductase NQO2, a flavoprotein that is phosphorylated in a chronic myelogenous leukemia cell line." (PMID 19236722, 2009).
colorectal adenocarcinoma (1 paper, 2025). The most common type of colorectal carcinoma. "Potential diagnostic transcripts may include ADH1C, GGT5, NQO2, and SLC25A5 in colorectal adenocarcinoma." (PMID 41465541, 2025).
colorectal cancer (1 paper, 2025). A primary or metastatic malignant neoplasm that affects the colon or rectum. "This study identified and validated a reproducible five-gene panel—DLG5, CD177, SH2D1B, NQO2, and KRT73—derived from whole-blood RNA, with strong diagnostic relevance for colorectal cancer (CRC)." (PMID 41373777, 2025).
fluorosis (1 paper, 2023). "In agreement with our previous report, we observed here that chronic fluorosis in rats was associated with dose‐ and time‐dependent increases in the level of the NQO2 protein in the brains of these animals." (PMID 36650666, 2023). "For investigating the mechanism of brain injury caused by chronic fluorosis, this study was designed to determine whether NRH:quinone oxidoreductase 2 (NQO2) can influence autophagic disruption and oxidative stress induced in the central nervous system exposed to a high level of fluoride." (PMID 36650666, 2023).
genital warts (1 paper, 2021). "In particular, imiquimod, a prescription medication used to treat genital warts, stimulates mtROS generation by inhibiting the quinone oxidoreductases NQO2 and mitochondrial Complex I, which triggers the NLRP3 inflammasome activation." (PMID 33414419, 2021).
leukemia (1 paper, 2009). A malignant (clonal) hematologic disorder, involving hematopoietic stem cells and characterized by the presence of primitive or atypical myeloid or lymphoid cells in the bone marrow and the blood. "To date, numerous crystal structures of the flavoprotein oxidoreductase NQO2 in complex with quinones, natural products, and xenobiotics have been solved, and we report here the x-ray crystal structure of NQO2 bound to the leukemia drug imatinib, an inhibitor of Bcr-Abl." (PMID 19236722, 2009).
liver cancer (1 paper, 2024). An epithelial or non-epithelial malignant neoplasm that arises from the liver. "Furthermore, Apigenin exerted a pro-autophagic effect mediated by activation of AMPK and direct binding of NRH-quinone oxidoreductase 2 (NQO2) in liver cancer cells." (PMID 38791608, 2024).
myelodysplastic syndrome (1 paper, 2022). A clonal hematopoietic disorder characterized by dysplasia and ineffective hematopoiesis in one or more of the hematopoietic cell lines. "NQO2 knockout mice developed myelodysplastic syndrome as a result of bone marrow cell hyperplasia and decreased apoptosis." (PMID 36142607, 2022).
non-small cell lung carcinoma (1 paper, 2022). A group of at least three distinct histological types of lung cancer, including non-small cell squamous cell carcinoma, adenocarcinoma, and large cell carcinoma. "Interestingly, the top-ranked protein NQO2 is linked to non-small cell lung cancer." (PMID 36014414, 2022).
stress-related disorder (1 paper, 2025). Stress-related disorders are mental health disorders that are a result of an atypical response to both short and long-term anxiety due to physical, mental, or emotional stress. "bHR-like animals also had upregulation of protective Mfge8 and upregulation of Nqo2, which can enhance reactive oxygen species production or reduce oxidative stress in a manner important for encoding novelty in hippocampal interneurons and potentially stress-related disorders." (PMID 40103584, 2025).
synucleinopathy (1 paper, 2022). A neurodegenerative disease that is characterized by the abnormal accumulation of aggregates of alpha-synuclein protein in neurons, nerve fibers or glial cells. "All NFE2L2,NQO2, and MAO-B converge in AD and PD disorders, as well as associatedtauopathy and synucleinopathy labels." (PMID 35245051, 2022). "The OpenTargets DB reveals common association of NFE2L2, NQO2, and MAO-B withseveral NDs, displaying visible convergence for PD and AD phenotypesas tauopathies and synucleinopathies." (PMID 35245051, 2022).
cancer (12 papers, 2014 to 2025). A tumor composed of atypical neoplastic, often pleomorphic cells that invade other tissues. "In fact, the deletion of NQO2 gene by CRISPR-Cas9 technology in HCT116 cancer cell line caused remarkably opposed changes in energy metabolism gene expression patterns compared to AD brains associated with microglia and astrocyte activation." (PMID 38254976, 2024). "This selective cytotoxicity in PRX1 knockdown cancer cells is associated with a significant cellular accumulation of H2O2 partially due to an overexpression of NRH:quinone oxidoreductase 2 (NQO2)." (PMID 26689287, 2015). "This yet-to-be-explored possibility might consolidate the notion that NQO2 indeed functions as a tumor suppressor in PTEN-deficient cancer cells." (PMID 24968355, 2014). "Curcumol exhibits synergistic lethal effects with TRAIL on cancer cell by directly targeting quinone oxidoreductase 2 (NQO2) to induce reactive oxygen species, triggering ER stress‐C/EBP homologous protein (CHOP)‐death receptor 5 (DR5) signaling to combat TRAIL‐resistant cancer." (PMID 33240775, 2020). "Among them, six melatonergic genes were significant unfavorable factors in cancers (e.g., MTNR1A in ESCA and LIHC; GPR50 in KIRC, LIHC, and STAD; NQO2 in BRCA, LIHC, and LUSC; CYP1B1 in KIRC and STAD; ASMT in ESCA, HNSC, and LUAD; and MTNR1B in STAD)." (PMID 33842355, 2021). "Differential expressions in the initial stage of cancer (CSI or CSI and CSII), such as for ADH1C, GGT5, NQO2, and SLC25A5 (bolded), may indicate them as candidates for diagnostic biomarkers." (PMID 41465541, 2025).
tumor (5 papers, 2014 to 2024). "Furthermore, HOXA11-AS knockdown and HOXA11-AS knockdown + NQO2 inhibition reduced the sphere-forming ability of the cells, but this tumor characteristic was only slightly diminished by NQO1 inhibition." (PMID 36142607, 2022). "In addition, compared to the lanthanide-mediated suppression of NQO1 alone, the inhibition of both NQO1 and NQO2 by HOXA11-AS knockdown markedly enhanced the suppression of tumor growth and metastasis, with a particularly strong effect in the latter." (PMID 36142607, 2022).
NQO2 also shares sentences with these, for which no sentence is quoted: neurodegenerative disease (3 papers); Alzheimer disease (2); amnesia (2); cognitive deficit (2); colon carcinoma (2); malaria (2); age (1); brain cancer (1); colitis (1); endothelial dysfunction (1); esophageal adenocarcinoma (1); esophageal cancer (1); glaucoma (1); memory impairment (1); neuroblastoma (1); neurological disease (1); neutropenia (1); osteoporosis (1); ovarian tumors (1); Stroke (1).